SEM1 (SEM1 26S proteasome subunit)
Description:
Component of the 26S proteasome, a multiprotein complex involved in the ATP-dependent degradation of ubiquitinated proteins. This complex plays a key role in the maintenance of protein homeostasis by removing misfolded or damaged proteins, which could impair cellular functions, and by removing proteins whose functions are no longer required. Therefore, the proteasome participates in numerous cellular processes, including cell cycle progression, apoptosis, or DNA damage repair. Component of the TREX-2 complex (transcription and export complex 2), composed of at least ENY2, GANP, PCID2, SEM1, and either centrin CETN2 or CETN3. The TREX-2 complex functions in docking export-competent ribonucleoprotein particles (mRNPs) to the nuclear entrance of the nuclear pore complex (nuclear basket). TREX-2 participates in mRNA export and accurate chromatin positioning in the nucleus by tethering genes to the nuclear periphery. Binds and stabilizes BRCA2 and is thus involved in the control of R-loop-associated DNA damage and thus transcription-associated genomic instability. R-loop accumulation increases in SEM1-depleted cells.
Synonyms: C7orf76; DSS1; SHFDG1; SHFM1; ECD; SHSF1; FLJ42280; PSMD15; SHFD1
Tractability: Small molecule: an approved drug acts on it; a structure with a bound ligand is known; a high-quality ligand is known. PROTAC: ubiquitination databases record sites on it.
Gene: Protein-coding gene on chromosome 7 (96,481,626 to 96,709,891, reverse strand). Ensembl gene ENSG00000127922.
Subcellular location: Nucleus
Subcellular location (Human Protein Atlas): Cytosol
Pathways (Reactome):
Immune System: AMPK-induced ERAD and lysosome mediated degradation of PD-L1(CD274); Activation of NF-kappaB in B cells; Antigen processing: Ubiquitination & Proteasome degradation; CLEC7A (Dectin-1) signaling; Cross-presentation of soluble exogenous antigens (endosomes); Dectin-1 mediated noncanonical NF-kB signaling; Downstream TCR signaling; ER-Phagosome pathway; FCERI mediated NF-kB activation; GSK3B-mediated proteasomal degradation of PD-L1(CD274); Interleukin-1 signaling; NIK-->noncanonical NF-kB signaling; SPOP-mediated proteasomal degradation of PD-L1(CD274); TNFR2 non-canonical NF-kB pathway
Cell Cycle: APC/C:Cdc20 mediated degradation of Securin; APC/C:Cdh1 mediated degradation of Cdc20 and other APC/C:Cdh1 targeted proteins in late mitosis/early G1; Autodegradation of Cdh1 by Cdh1:APC/C; Autodegradation of the E3 ubiquitin ligase COP1; Cdc20:Phospho-APC/C mediated degradation of Cyclin A; FBXL7 down-regulates AURKA during mitotic entry and in early mitosis; G2/M Checkpoints; SCF(Skp2)-mediated degradation of p27/p21; SCF-beta-TrCP mediated degradation of Emi1; Separation of Sister Chromatids; The role of GTSE1 in G2/M progression after G2 checkpoint; Ubiquitin-Mediated Degradation of Phosphorylated Cdc25A; Ubiquitin-dependent degradation of Cyclin D
Signal Transduction: Asymmetric localization of PCP proteins; Degradation of AXIN; Degradation of DVL; Degradation of GLI1 by the proteasome; Degradation of GLI2 by the proteasome; Degradation of beta-catenin by the destruction complex; GLI3 is processed to GLI3R by the proteasome; Hedgehog 'on' state; Hedgehog ligand biogenesis; MAPK6/MAPK4 signaling; Negative regulation of NOTCH4 signaling; Regulation of PTEN stability and activity; Regulation of RAS by GAPs
and 38 more pathways
Gene Ontology:
Biological process: double-strand break repair via homologous recombination
Cellular component: proteasome complex
Genetic constraint (gnomAD): Loss-of-function variants: 0 observed, 3.96 expected, observed/expected ratio (o/e) 0, 90% interval 0 to 0.75. That is too few expected variants to judge how well the gene tolerates losing a copy. Missense variants: 32 observed, 30.83 expected, observed/expected ratio (o/e) 1.04, 90% interval 0.78 to 1.39. Synonymous variants: 15 observed, 11.97 expected, observed/expected ratio (o/e) 1.25, 90% interval 0.83 to 1.82.
Homologues: Orthologues: guinea pig SEM1 (100% identical), macaque SEM1 (100% identical), mouse Sem1 (100% identical), rat Sem1 (100% identical), zebrafish sem1 (97% identical), tropical clawed frog sem1 (66% identical).
Diseases named in the same sentence as SEM1 in open-access papers:
SEM1 is named in the same sentence as 17 diseases in open-access papers, as found by Europe PMC text mining. Sharing a sentence is not in itself a finding about the gene and the disease. The quoted sentences say what the papers report.
melanoma (2 papers, 2021 to 2022). A malignant, usually aggressive tumor composed of atypical, neoplastic melanocytes. "SEM1 overexpression is highly correlated with poor prognosis in patients with melanoma and squamous cell carcinoma." (PMID 34209254, 2021).
seminoma (2 papers, 2022 to 2023). A radiosensitive malignant germ cell tumor found in the testis (especially undescended), and extragonadal sites (anterior mediastinum and pineal gland). "To this end, we modulated PTTG1 protein levels in JKT-1 and SEM-1 seminoma cell lines, which show a more aggressive phenotype among the seminoma lines, and we evaluated the expression of E-CAD, since it is known that its decreased expression is one of the earliest steps in the EMT process." (PMID 36230799, 2022). "To validate the interaction between PTTG1 and spectrins and their differential reciprocal binding in JKT-1, SEM-1, and TCAM2 seminoma cells, we performed PTTG1 immunoprecipitation and immunofluorescence analysis." (PMID 38069214, 2023). "Thereafter, we made use of in vitro cellular model of seminoma to demonstrate the correlation between nuclear PTTG1 and a more aggressive phenotype in the JKT-1, SEM-1, and TCAM2 cell lines." (PMID 38069214, 2023). "To find out the differential partners involved in the subcellular localization of PTTG1, we performed immunoprecipitation of the securin from the lysates of multiple seminoma cell lines, including JKT-1, SEM-1, and TCAM2." (PMID 38069214, 2023).
Sepsis (1 paper, 2023). Sepsis is defined as life-threatening organ dysfunction caused by a dysregulated host response to infection. "Genes that participate in this pathway and were differentially expressed in our sepsis patients include PSMB1, NFKB2, SEM1, UBB and RELA." (PMID 37731199, 2023).
thyroid cancer (1 paper, 2024). "NHEJ- (XRCC6, XRCC5, PRKDC) and HR‐ (SSBP1, SEM1, RPA2, RPA3)-related genes were found to be expressed in both normal follicular and thyroid cancer cells." (PMID 38380364, 2024). "NHEJ- (XRCC6, XRCC5, PRKDC) and HR- (SSBP1, SEM1, RPA2, RPA3) related genes are expressed by both normal follicular and thyroid cancer cells." (PMID 38380364, 2024).
tumor (8 papers, 2011 to 2025). "Although the most frequent variant, found in all the tumor groups, p.Gln59Pro is widespread in the human population (maximum allele frequency (AFmax) of 0.88); still, the overall number of SEM1 variants was significantly higher in BOT than in either lgOvCa or hgOvCa." (PMID 39456660, 2024). "One of these genes, SEM1, which codes for a 26S proteasome subunit, was very often altered in all the tumor groups." (PMID 39456660, 2024). "As proven in the present study, the list of genes from the 44-gene panel more frequently mutated in BOT compared to the other tumor groups (FANCB, SEM1, FANCA, BRCA2, CHEK2, MUTYH, RAD50) was much longer than analogically altered genes in the hot-spot panel (KRAS only)." (PMID 39456660, 2024). "Likewise, primary TNBC patients’ tumor samples (CRDCA, SEM‐1, and ARI‐1) also showed increased expression of E‐cadherin, active β‐catenin, and ALDH but decreased expression of YAP and CD44." (PMID 29316250, 2018).
cancer (6 papers, 2013 to 2021). A tumor composed of atypical neoplastic, often pleomorphic cells that invade other tissues. "The lncRNA GPRC5D-AS1 with CNVs driving the dysregulation of downstream cancer genes such as PRKCI, SEM1, TBL1XR1, IMPACT, and RPL22L1 further disturbed the activities of NOTCH signaling pathway that is usually inactivated in LUSC." (PMID 34925461, 2021). "Furthermore, WRS and SEM1, downregulated genes in GSTM3 downregulation, showed poor correlation with treatment outcomes in patients with cancer." (PMID 34209254, 2021).
SEM1 also shares sentences with these, for which no sentence is quoted: breast carcinoma (2 papers); B‐cell lymphomas (1); gastric cancer (1); glioma (1); hearing loss (1); infection (1); myeloma (1); skin cancer (1); squamous cell carcinoma (1); triple-negative breast carcinoma (1); viral infection (1).